IL6 (interleukin 6)
Diseases named in the same sentence as IL6 in open-access papers (continued):
Sharing a sentence is not in itself a finding about the gene and the disease.
Stroke (continued). "As opposed to these studies, which proposed a role for cerebral MCs in worsening stroke pathology, another study (reviewed in detail below), proposed that meningeal, rather than cerebral, MCs play important roles in exacerbating stroke pathology, in part by secreting IL-6." (PMID 31001088, 2019). "Furthermore, the levels of the inflammatory and anti-inflammatory cytokines such as IL-1β, IL-6, and IL-10, at the early stage of stroke might serve as important biomarkers to predict the prognosis for ischemic stroke patients." (PMID 30705764, 2019). "IL-6 is also critical to social support-mediated improvement in neurogenesis after ischemic stroke, indicating astrocytic IL-6 could promote post-stroke neuroangiogenesis." (PMID 31133816, 2019). "Thus, age might be an important intrinsic factor determining the level of microglia activation as well as the production of inflammatory cytokines such as IL-1β and IL-6 after stroke." (PMID 30705764, 2019). "Furthermore, an in vivo study showed that IL-6 produced locally by resident brain cells could promote post-stroke angiogenesis and long-term functional recovery." (PMID 31133816, 2019). "In light of recent findings suggesting that hyperforin could promote angiogenesis and astrocytic IL-6 is essential to angiogenesis after ischemic stroke, we sought to investigate whether hyperforin treatment during stroke recovery could increase the IL-6 expression by astrocytes." (PMID 31133816, 2019). "Indeed IL-6 has been seen to have neurotrophic and anti-inflammatory effects; in the stroke study IL-6 and TNF-α were inversely correlated, suggesting IL-6 might counterbalance the potential detrimental effects of TNF-α." (PMID 28253907, 2017). "Also, high plasma IL-6 levels correlate with the severity of stroke." (PMID 28115020, 2017). "Therefore, the post-stroke plasma increases in IL-6 and CXCL1 found in obese mice here could be due to increased release from the adipose tissue." (PMID 28798136, 2017). "Both MCP-1 and IL-6 are associated with pro-inflammatory macrophages, which we interpret to mean that in both humans and mice the macrophage response to stroke does not resolve towards a reparative tissue remodeling phenotype as efficiently as the macrophage response to damage in other tissues." (PMID 27600707, 2016). "TNF, IL-1 and IL-6 strongly affect the development of ischemic brain damage in animal models, and their levels are increased in the blood and in the cerebrospinal fluid of stroke patients, thus attracting considerable interest as putative markers of stroke severity and neurologic outcome." (PMID 25972779, 2015). "For determination if initial levels (at 6 h) of IL-10, IL-6 and CRP are independently associated with infection in ischemic stroke patients, we performed a binary logistic regression analysis that was adjusted for NIHSS on admission, stroke etiology, and peak levels of S100B." (PMID 25613713, 2015). "Furthermore, IL-6 and CRP are independent risk factors for stroke and myocardial infarction." (PMID 25574216, 2015). "Because white blood cell (WBC) count, hsCRP, TNFα, and IL-6 are reported to be independent parameters predicting stroke outcomes, we are interested in whether leukocyte ROCK activity correlates with these inflammatory cytokines in acute ischemic stroke patients." (PMID 24716192, 2014). "Furthermore, blood levels of IL-6 were significantly higher in the stroke patients who died." (PMID 25295149, 2014). "Importantly, whereas in the CNS the increased post-ischemic levels of IL-6 have been suggested to be beneficial, peripheral IL-6 levels correlate well with both stroke severity and poor clinical outcome, suggesting IL-6 to be a marker of harmful inflammation in clinical stroke." (PMID 23957944, 2013). "Therefore, IL-6 may be a key mediator of the reduced inflammatory reaction following stroke in aged mice." (PMID 22028848, 2011).
Stroke (continued). "Thus, according to the present research, IL-6 tends to reflect the severity of the stroke even at six hours post-injury and may play a key role in inflammatory damage caused by ischemia." (PMID 21450100, 2011). "However, IL-6 can upregulate IL-1ra, and IL-6-deficient mice do not show improved outcome after stroke." (PMID 21040547, 2010). "Mice deficient in IL-6 showed similar stroke volume and disability at 24 h as mice with normal IL-6 expression, suggesting that it may simply be part of the inflammatory response to stroke and not directly pathogenic." (PMID 19901973, 2009). "As continuous variables, IL-6 (p = 0.02), CRP (p = 0.03), MMP-9 (p = 0.004), D-dimer (p < 0.001), LDL (p = 0.03), von Willebrand factor (p = 0.10), and factor VIII activity (p = 0.10) were positively associated with stroke, whereas HDL-3 was inversely associated (p = 0.02) with stroke." (PMID 17571161, 2007). "The combined effects of IL-6 and TNF-α levels provide important insight into how UMC119-06 influences immune modulation in stroke recovery." (PMID 41583506, 2026). "Systemic inflammation is a primary response following stroke and can be evaluated by measuring markedly upregulated pro-inflammatory cytokines, such as TNF-α, IL-6, and IL-1β." (PMID 41598337, 2026). "A large body of preclinical research has confirmed that in experimental stroke models, VNS can significantly reduce infarct volume, lower the levels of pro-inflammatory cytokines (e.g., TNF-α, IL-6) in serum and brain tissue, and improve neurological outcomes." (PMID 41601622, 2026). "During systemic inflammation or localized CNS disorders (e.g., stroke, neuroinflammation), proinflammatory cytokines (TNF‐α, IL‐1β, and IL‐6) enhance BBB permeability by disrupting tight junction (TJ) proteins (e.g., occludin) in endothelial cells." (PMID 41583906, 2026). "Studies have shown that the levels of acetic, propionic, and butyric acids are lower in stroke patients and older individuals, and butyric acid mitigates the production of TNF-α and IL-6 induced by LPS." (PMID 40004026, 2025). "Similar to CHD and HF, higher concentrations of GDF15 and IL6, along with TNFR1, Eotaxin, MMP1, and MMP2, conferred the highest HRs for incident stroke." (PMID 39695064, 2025). "The use of anti-inflammatory agents to modulate IL-6 and TNF-alpha levels in stroke patients is currently under investigation." (PMID 39859987, 2025). "In stroke models, GLP-1RA therapy mitigates astrocyte-derived damage: experimental data show GLP-1R agonists reduce astrocytic release of MMP-9, IL-1, and IL-6 that otherwise disrupt the blood–brain barrier." (PMID 41462689, 2025). "In contrast, other studies, using a rat stroke model, demonstrated that 5 days after the model induction, ICVIGF-1 increased IL-6 plasma concentration, but the intraperitoneal injection of IGF-1 reduced this concentration." (PMID 40801621, 2025). "As reported by others, for six proteins we observed opposite directionality of associations for plasma versus CSF protein levels (APOE, EPO, PSMP, PRSS8 and TFPI with WMHs, IL-6 with HIP-PVS, and BT3A2 with stroke)." (PMID 41266628, 2025). "Ischemia reperfusion significantly increases IL-6 and TNF-α levels in the injured cerebral area during the subacute phase of stroke." (PMID 40004043, 2025). "Elevated IL-6 and TNF-alpha levels during the acute phase of stroke have been shown to exacerbate neuronal injury through various mechanisms, including apoptosis and disruption of the blood–brain barrier." (PMID 39859987, 2025). "Although the precise effects of YHJGs on AP-1 and NF-κB remain to be experimentally validated, the observed reduction in IL-1β, IL-6, and TNF-α suggests that YHJGs hold promise as a therapeutic agent for stroke-related inflammation." (PMID 41011203, 2025). "pronounced elevations in IL-1β, IL-6, TNF-α, MCP-1, and IFN-γ at day 1 post-stroke, exacerbated by bacterial injection." (PMID 40581646, 2025).
Stroke (continued). "A 2023 study found elevated levels of serum ferritin, CRP, D-dimer, and IL-6 in post-stroke patients: CRP was elevated in 100%, D-dimer in 87%, and ferritin and IL-6 in 60%." (PMID 41362543, 2025). "Key inflammatory cytokines in stroke include interleukin-1 (IL-1), TNF-α, interleukin-6 (IL-6), interleukin-10 (IL-10), and transforming growth factor-β (TGF-β)." (PMID 40362194, 2025). "In terms of inflammatory response, treadmill training significantly decreased the concentrations of IL-6 and IL-17 and increased the levels of IL-10 and TGF-β, suggesting that exercise has a modulating effect on post-stroke inflammation." (PMID 40837062, 2025). "Inflammatory cytokines such as IL-1β, IL-6, and TNF-ɑ increased within 24 h, peaked 2∼3d, and remained at high levels for several months after stroke onset." (PMID 40144659, 2025). "Recent studies also suggest that elevated levels of IL-6 and TNF-α assessed on days 1 and 7 significantly correlate with greater stroke severity and worse functional outcomes, as indicated by higher NIHSS and mRS scores." (PMID 40305179, 2025). "For example, increased IL-6 and TNF-α levels during the acute phase correlate with larger infarct volumes and higher disability scores at three months post-stroke." (PMID 40869247, 2025). "Specifically, IL6 signaling through the Janus kinase (JAK) and signal transducer and activator of transcription 3 (STAT3) pathway plays a major role in post-stroke inflammatory responses through the transcription of various inflammatory genes." (PMID 40362325, 2025). "Here, we examined the mRNA expressions of IL-1β, IL-6 and TNF-α after 7 d of stroke, which are crucial for the cerebral ischemia-induced neuroinflammatory process." (PMID 40004043, 2025). "The inflammatory mediators produced in periodontal diseases, including IL-6, TNF-α, and C-reactive protein, promote atherogenesis and thromboembolic events, which can contribute to stroke pathogenesis." (PMID 40259824, 2025). "We selected the common features of LDH, WBC, NIHSS, IL-6 and their SHAP values and GINI index from these two models, and constructed a stroke recurrence model (hereinafter referred to as the recurrence model) according to the formula in the method." (PMID 40917676, 2025). "Both primary outcomes (major cardiovascular events including myocardial infarction, stroke, and recurrent ischemia) and secondary outcomes (reduction of inflammatory biomarkers such as hs-CRP and IL-6 and incidence of adverse effects) were assessed." (PMID 40688868, 2025). "The patients included in our research demonstrated significant correlations between the biomarkers IL-6 and TNF-alpha and the modified Rankin Scale, highlighting the crucial role of inflammation in the disability prognosis of stroke patients." (PMID 39859987, 2025). "IL-6 serves as an important driver of the inflammatory responses in patients with AIS, with increased serum levels demonstrating strong correlations with stroke severity and neurological." (PMID 41368357, 2025). "Among monocytic markers, reduced expression of mHLA-DR and elevated levels of IL-6 and LBP were related to poor outcomes in stroke patients." (PMID 40490740, 2025). "Phase II studies demonstrated that anakinra administered within 6 h of stroke onset was safe and led to reductions in circulating neutrophils, CRP, and IL-6 levels, suggesting systemic anti-inflammatory effects." (PMID 40869247, 2025). "Treg cells express high levels of amphiregulin (Areg) and OPN, which are thought to inhibit IL-6 and STAT3 pathways in microglia and astrocytes after stroke and reduce inflammation." (PMID 40289984, 2025). "As we move forward, the exploration of novel anti-inflammatory treatments targeting IL-6 and TNF-alpha presents promising avenues for improving post-stroke recovery and reducing long-term disability." (PMID 39859987, 2025). "In the RF model, WBC, NIHSS, Age, IL-6, and LDH are the top 5 most important characteristics that affect the degree of stroke recurrence." (PMID 40917676, 2025).
Stroke (continued). "The qPCR analysis showed that the mRNA levels of IL-6, IL-1β and TNF-α were increased in the stroke area." (PMID 40313968, 2025). "NPAS4 deficiency in mice results in an increase in activated microglia and astrocytes as well as increased protein levels of IL-6 and TNF-α after stroke." (PMID 37938766, 2024). "Inflammatory response was determined by detecting levels of cytokines (interleukin-2 [IL-2], IL-4, IL-5, IL-8, IL-6, IL-10, IL-12p70, IL-17, tumor necrosis factor-α [TNF-α], interferon-γ [IFN-γ], IFN-α, and IL-1β) within 14 days after stroke onset." (PMID 38902691, 2024). "Research showed that H. pylori infection induced the production of pro-inflammatory cytokines, including IL-1β, IL-6, and TNF-α in gastric epithelial cells, contributing to gastric inflammation and potentially to systemic conditions such as stroke." (PMID 39202269, 2024). "Cytokines released during stroke, such as TNF-α, IL-1β, and IL-6, further activate the inflammatory response and induce cell death." (PMID 38742047, 2024). "Authors concluded that IL-6 and MIP-1α measured at baseline and 18 months post-stroke were the most promising for assessing and monitoring post-stroke cognitive impairment." (PMID 41542283, 2024). "Numerous studies have shown a remarkable elevation in IL-6, TNF, CRP, and neutrophils in patients with stroke." (PMID 38699426, 2024). "The levels of MPO-DNA, PAD4, C1q, IL-1β, IL-6, IL-8 and HMGB1 change significantly over time during the acute phase of stroke (all P < 0.05)." (PMID 39737165, 2024). "Compared to ND, HFD increased plasma levels of the proinflammatory cytokines TNF-α, IL-6, IL-23, and MCP-1 in stroke mice." (PMID 39845972, 2024). "TMAO manifests opposite effects given that it can directly activate platelets, augmenting the likelihood of thrombosis and stroke as well as increasing the expression of pro-inflammatory cytokines, such as TNF-α, IL-6, and C reactive protein." (PMID 38787240, 2024). "Genes related to inflammation such as Ccl5, Cxcl5, Il1a, Tnfsf10, Nfkb1, Tnfrsf1b, Ccr7, Tnfrsf9, Ccl7, Il1b, Il6, and Ccl24 were also downregulated upon MMP-3 KO in male stroke brains." (PMID 39000490, 2024). "In an independent experimental group, IL-6 and TNF-α, used as markers of inflammation after stroke, were analyzed in ischemic mice before and after the treatment with the vehicle and CSM@rtPA." (PMID 38166940, 2024). "Levels of TNF-α, TNF-γ, IL-6, MCP-1, and IL-2 were significantly increased at 6 and 22 h after MCAO in mice with stroke injuries." (PMID 39081338, 2024). "We found higher amounts of inflammatory cytokines like TNF- α and IL-6 and chemokine MCP-1 in the plasma of HFD compared to ND stroke mice." (PMID 39845972, 2024). "Macrophages, as the main cells of the peripheral immune system, have been proved to participate in the prognosis of stroke via secreting pro-inflammatory cytokines, such as TNF-α and IL-6, and anti-inflammatory cytokines, such as IL-10." (PMID 37199575, 2023). "The main specific targets proposed for stroke therapies are the cytokines TNF-α, IL-1β, and IL-6, and the adhesion molecule ICAM-1, which will be discussed in this section." (PMID 37762627, 2023). "In the present study, there was increased activity of TNF-α, IL-6, and IL-1β in the MCAO-induced animal group indicating the brain injury during the stroke." (PMID 35838888, 2023). "Combination of T2DM and stroke had a super-additive effect on the increased expression of SAA and IL6." (PMID 36968490, 2023). "In a rat model of global stroke, a pinocembrin treatment administered daily for 7 days before a stroke decreased the infarct size and NF-κB, TNF-α, and IL-6 in the hippocampal tissue." (PMID 36901731, 2023). "12/15-LOX inhibition significantly decreased IL-1beta, IL-6, and TNF-alpha protein levels at 24-h of stroke." (PMID 37822799, 2023). "In this study were analysed glutamate, IL-1β, IL-6, IL-10 and TNF-α according to the time of stroke." (PMID 36835156, 2023).
Stroke (continued). "Exploratory secondary analysis also gave positive signal towards functional outcome after stroke, with circulating neutrophils, CRP and IL-6 being suppressed in the treatment arm as compared to the placebo one." (PMID 36745280, 2023). "Consistent with previous studies, the dramatic increase in stroke-induced inflammatory cytokines TNF-α, IL-1β, and IL-6 was suppressed after treatment with NSC-EV." (PMID 37691119, 2023). "In T2DM mice, stroke induced earlier and higher TLR4, NLRP3, and cytokine expression (SAA, IL1β, IL6, TNFα) in the liver compared to heart and kidney, as measured by Western blot." (PMID 36968490, 2023). "The results of this study indicate that the levels of plasma iFABP, IL-6, and TNF-α in the PSD group are significantly higher compared to that in the stroke group." (PMID 38084247, 2023). "Stress in stroke stimulates peripheral immune cells to secrete pro-inflammatory cytokines, TNF-α, IL-1β and IL-6, which can cross the BBB and further activate microglia and astrocytes in the CNS to secrete more pro-inflammatory cytokines." (PMID 37199575, 2023). "Real-time PCR analysis in rats after t-MCAO has revealed that the mRNA levels for TNF-a, IL-1b, IL-6, E-selectin, and ICAM-1 are increased 3 h after stroke that persist for 24 h in the hemisphere ipsilateral to occlusion." (PMID 37342100, 2023). "At 24 h post-stroke, CCL2 and IL-6 were significantly upregulated following a single dose of HFI419." (PMID 37957163, 2023). "Recent meta-analyses have shown that colchicine positively reduces the incidence of MACE, MI, stroke, and revascularization and decreases cardiovascular events, inflammatory markers, hs-CRP, and IL-6 in patients with coronary artery disease." (PMID 36873405, 2023). "As important immunological mediators in post-stroke responses, cytokines have been confirmed as independent predictors of SAP, including IL-6, IL-10, and TNFα." (PMID 37065465, 2023). "In the same model, kaempferol administered for 7 days after stroke also decreased the NF-κB and pro-inflammatory cytokines such as IL-5, TNF-α, IL-1β, and IL-6, but the reduction of last three cytokines only occurred with high doses." (PMID 36901731, 2023). "In this study, a higher concentration of inflammatory biomarkers IL-6, and TNF-α within 4.5, 24 h and 7 days after the onset of stroke was observed compared to healthy participants who acted as a control group." (PMID 36142524, 2022). "Poncirin suppressed the LPS-induced production of inflammatory cytokines TNF-α and IL-6 in RAW 264.7 macrophages and attenuated ischemic injury in stroke mice." (PMID 36185646, 2022). "In summary, these studies suggest that genetic or pharmacological inhibition of these pro-inflammatory mediators (iNOS, IL-6, CCL2, and CCL9) provides neuroprotection against stroke, which can affect pro-inflammatory mediators by modulating LCN-2." (PMID 35493318, 2022). "We found that the predictive value of IL-6 and YKL-40 in recurrent stroke, composite vascular event and poor functional outcome among the patients with acute ischemic stroke or TIA was more apparent than that of hsCRP and Lp-PLA2 mass and activity." (PMID 35761288, 2022). "The current study, therefore, investigated the associations between SNPs of inflammatory molecules, consisting of IL-1β, TNF-α, IL-6, IL-10, IL-18, interferon-γ (IFN-γ) and C-reactive protein (CRP), and PSD at 2 weeks after stroke (early-onset PSD)." (PMID 36225923, 2022). "When simultaneously considering all markers, IL-6 and YKL-40 remained predictive for recurrent stroke and poor functional outcome." (PMID 35761288, 2022). "In an experimental stroke model, the cytokines IFN-γ, IL-6, and CXCL1 are elevated in the serum within a matter of hours, and circulating and splenic immune cells increase the production of IL-6, IL-2, TNF-α, IFN-γ, and CCL2." (PMID 36446955, 2022).